VWF (von Willebrand factor)
Diseases named in the same sentence as VWF in open-access papers (continued):
Sharing a sentence is not in itself a finding about the gene and the disease.
COVID-19 (continued). "This explains the significant changes in platelet VWF/GP Ib-IX-V levels in patients with COVID-19 in the present study, and further indicates that the cascade initiated by the VWF/GP Ib-IX-V complex may play a pivotal role in the activation and regulation of platelets by SARS-CoV-2 infection." (PMID 35139909, 2022). "Clinical markers for indicating the activation of coagulation and fibrinolysis, including d-dimer and Von Willebrand factor (VWF), were significantly elevated in COVID-19 patients and were predictive of poor outcome, further supporting the hypothesis of SARS-CoV-2-induced endothelial damage." (PMID 35741101, 2022). "Thus, vWF activity may predict mortality during systemic inflammatory syndrome, including COVID-19 worse situations." (PMID 35268474, 2022). "It is currently believed that in addition to being a respiratory disease, COVID-19 might also be a ‘vascular disease’, as it may result in a leaky vascular barrier and increased expression of von Willebrand factor (VWF), responsible for increased coagulation, cytokine release, and inflammation." (PMID 34694226, 2021). "However, a significant alteration in the platelet-vWF-ADAMTS13 axis was found among COVID-19 patients, including high vWF levels with high platelet counts and an increase of 3–7 fold of vWF antigen to ADAMTS13 activity ratio that was strongly associated with COVID-19 severity." (PMID 34372552, 2021). "In addition, the elevated levels of VWF were also observed in mild COVID-19 patients." (PMID 34769508, 2021). "Indeed, D-dimer, plasminogen activator inhibitor 1 (PAI-1), and Von Willebrand factor (VWF) are elevated in COVID-19 patients and may indicate hypercoagulable states and/or endothelial damage that can lead to stroke and other vascular complications." (PMID 34511868, 2021). "Indeed, plasmatic level of vascular cell adhesion molecule-1 (VCAM-1), intercellular adhesion molecule 1 (ICAM-1), plasminogen activator inhibitor-1 (PAI-1), tissue factor (TF), and von Willebrand factor (vWF) antigens and activities are all elevated in severe COVID-19 cases." (PMID 35111777, 2021). "Based on these observations, the vWF/ADAMTS13 imbalance has been proposed to be causally related both to the prothrombotic tendency and to the microvascular pulmonary thrombosis, which subtend to a form of thrombotic microangiopathy (TMA) observed in severe COVID-19 patients." (PMID 34834519, 2021). "Thus, COVID-19 induced hypoxia may upregulate VWF levels, and this has been supported by the clinical observation of rising VWF levels with increased oxygen requirements in a few COVID-19 patients." (PMID 34575297, 2021). "Therefore, they might have a secondary but indirect effect on COVID-19 pathophysiology mediated by VWF and FVIII." (PMID 33806540, 2021). "Although factor V, factor VII, factor VIII, and VWF are increased in initial SARS-CoV-2 infection, which generally indicates increased complications, factor V was seen to increase then decrease, which can complicate its use in the prediction of COVID-19-associated complications." (PMID 34829418, 2021). "Investigations into coagulation profiles have highlighted a heightened VWF(Ag)/ADAMTS13 ratio, especially in severe COVID-19 cases." (PMID 39941459, 2025). "Hemostatic alterations observed in COVID-19 include increased levels of coagulation factor VIII, elevated D-dimer, fibrinogen, and VWF." (PMID 40993743, 2025). "An imbalance in the von Willebrand factor (vWF)/ADAMTS13 axis and activation of the complement system occur concomitantly in COVID-19 patients and are significantly more pronounced in those with severe disease." (PMID 40508203, 2025). "Increasing evidence suggests that COVID-19 is primarily an endothelial disease, characterized by elevated levels of PAI-1 and vWF, heightened platelet activation, and a hypercoagulable state, resulting in venous, arterial, and microvascular thrombosis." (PMID 40612950, 2025).
COVID-19 (continued). "The FVIII/vWF ratio provides additional insight into FVIII dysregulation, and recent findings from COVID-19 have further highlighted FVIII’s role in hypercoagulability." (PMID 40429442, 2025). "Central to COVID-19 pathogenesis is a thrombo-inflammatory process, with elevated levels of factor VIII, von Willebrand factor (VWF), and D-dimer being key markers indicative of a hypercoagulable state." (PMID 39941459, 2025). "COVID-19+ women exhibited significantly lower FVIII, FXIII, plasminogen, higher VWF levels, decreased peak thrombin and enhanced clot lysis vs. controls." (PMID 40303405, 2025). "The dedicated, prospective design to investigate the role of the vWF/ADAMTS13 axis and complement activation, in order to clarify the issue of COVID-19 coagulopathy as a possible secondary TMA, is the main strength of our study." (PMID 40508203, 2025). "Our findings highlight the simultaneous activation of both the vWF/ADAMTS13 axis and the complement system in severe COVID-19 cases." (PMID 40508203, 2025). "Elevated levels of fibrinogen, von Willebrand factor (VWF), and the fibrin degradation product D-dimer in the blood indicate the presence of a COVID-19-specific coagulopathy." (PMID 40430138, 2025). "Elevations in D-dimer, von Willebrand factor (VWF), and factor VIII levels are commonly observed in patients with severe COVID-19." (PMID 39777702, 2025). "Severe COVID-19 is characterized by a hypercoagulable state, with significantly elevated FVIII and vWF levels, contributing to widespread microvascular and macrovascular thrombosis." (PMID 40429442, 2025). "Instead, they should be considered exploratory, emphasizing the need for further investigation into the role of low-frequency and rare variation in the VWF and ADAMTS13 genes in critical COVID-19." (PMID 41585277, 2025). "The selection of the rs657152 and rs505922 variants for these functional assays was informed by substantial prior evidence linking these SNPs to phenotypes including VWF levels, VTE, and COVID-19." (PMID 41311061, 2025). "Clusters A to C contain proteins with lower levels in COVID-19 convalescents, e.g. proteins functioning in cell adhesion and platelet degranulation (e.g. fibrinogen A (FGA), VWF), and innate immunity/the complement system (e.g. C1R, C1S, C1QA, C1QC, and GGH)." (PMID 38396092, 2024). "Elevated vWF/ADAMTS-13 ratios have been observed in sepsis and COVID-19 and are positively correlated with high ICU mortality." (PMID 38921594, 2024). "Elevated circulating levels of pro-coagulant factors such as von Willebrand factor (vWF), factor VIII (FVIII) or tissue factor (TF) were found in a high number of patients with COVID-19." (PMID 38225643, 2024). "A higher VWF/ADAMST-13 ratio, together with endothelial injury, coagulopathy, and poor prognosis, has been found in cases of acute and long COVID-19." (PMID 39199353, 2024). "This reduction in antithrombotic activity is characterized by increased levels of von Willebrand factor (vWF), fibrinogen, and factor VIII in COVID-19 patients." (PMID 39062549, 2024). "Endothelial cell biomarkers, including von Willebrand factor (vWF) antigen, vWF pro-peptide, and factor VIII, are significantly elevated in convalescent COVID-19, suggesting a persistent endotheliopathy." (PMID 38673677, 2024). "Further research on the VWF and ADAMTS13 axes in larger cohorts is needed to better understand how obesity interacts with COVID-19 pathogenesis and outcomes." (PMID 38608066, 2024). "Moreover, the VWF could be involved in local angiogenesis in severe COVID-19." (PMID 38378550, 2024). "We show reduction of elevated Factor VIII and VWF and VWF Ag:ADAMTS 13 ratio in the context of persistent inflammation, and the potential for PEX to safely and effectively reduce pro-thrombotic mediators in COVID-19." (PMID 39043682, 2024). "Recently, the vWF/ADAMTS-13 axis has emerged as a potential therapeutic target for both sepsis and COVID-19." (PMID 38921594, 2024).
COVID-19 (continued). "Coagulopathy in COVID-19 is characterized also by elevated levels of factor VIII and von Willebrand factor (vWF) and decreased ADAMTS13 activity." (PMID 39457048, 2024). "The exposure of CAEC to post-COVID-19 serum generates oxidant stress and stimulates CAEC to produce pro-inflammatory cytokines: IL-6, vWF, tP, and PAI-1." (PMID 38188630, 2023). "Serum vWF levels and ADAMTS13 activity are positively and negatively correlated with COVID-19 severity, respectively." (PMID 36941580, 2023). "However, whether VWF has an effect on angiogenesis in COVID-19 remains speculative." (PMID 37333991, 2023). "Elevated levels of vWf and PAI-1, and decreased ADAMTS-13 activity, demonstrate that COVID-19 is an endotheliopathy that shares features with thrombotic microangiopathy." (PMID 37175942, 2023). "In addition, microRNA cargo of EVs could contribute to the pathogenesis of thrombotic complications in COVID-19 patients by downregulating two specific miRNAs (miR-145 and miR-885) that promote higher levels of TF and von Willebrand Factor, thus determining a prothrombotic state." (PMID 36768242, 2023). "Multiple studies have noted a correlation between elevated VWF aggregation (up to five-fold), reduced ADAMTS13 activity, and elevated markers of coagulation in COVID-19 patients." (PMID 37159776, 2023). "Il-6, D-dimer, VWF, CRP, and PCT seem to be good COVID-19 biomarkers that are easy to perform in clinical practice." (PMID 37489362, 2023). "A marker of endothelial damage, von Willebrand factor (VWF), which promotes platelet activation and, in turn, coagulation, has been found to be significantly elevated in COVID-19 patients." (PMID 38069362, 2023). "Incubating endothelial cells with plasma from ICU COVID-19 patients for 10 min induced WPB exocytosis and secretion of vWF." (PMID 37526812, 2023). "Such a reduction in antithrombotic activity is marked by an increase in von Willebrand factor (vWF), fibrinogen, and factor VIII in COVID-19 patients." (PMID 37092518, 2023). "Initially described as elevated among other markers of endotheliopathy and glycocalyx damage, von Willebrand factor (VWF) seems to even more accurately predict outcomes, especially mortality, in patients with COVID-19 [21,22,]." (PMID 37333991, 2023). "It should be noted that fluctuations in the values of vWF antigen and ADAMTS-13 activity during COVID-19 occur within relatively narrow limits, which reduces the reliability of the forecast." (PMID 38132876, 2023). "One of the linking elements between vWF and NET formation is possibly IL-6, having a central role in the cytokine release syndrome of COVID-19." (PMID 36768817, 2023). "In a nutshell, the interaction between fibrin(ogen), D-dimer, P-selectin, VWF, and biomarkers like MMPs, ADAMTS-13, renal NGAL, PUMP, and TMPRSS2 intertwine within the context of acute COVID-19." (PMID 38077924, 2023). "In COVID-19, the ADAMTS13/vWF ratio decreases, leading to an excess of overactive UL-vWF multimers as a key driver of microthromboses in the pulmonary vasculature and SARS-CoV-2-associated ARDS." (PMID 36979908, 2023). "Markedly elevated levels of von Willebrand factor (vWf) and factor VIII are common in COVID-19 patients." (PMID 37373613, 2023). "In summary, the interaction between fibrin(ogen), D-dimer, P-selectin, VWF, and the mentioned biomarkers like MMPs, ADAMTS-13, renal NGAL, PUMP, and TMPRSS2 intertwines within the context of acute COVID-19." (PMID 38077924, 2023). "More importantly, plasma levels of VWF and the ratios of VWF/ADAMTS13 were persistently elevated in patients with COVID-19 throughout hospitalization." (PMID 38002786, 2023). "Omicron, for example, is more prevalent but less severe, and despite pulmonary embolism being less frequent, 1 study showed that clotting parameters (not including VWF) are still significantly elevated but may be lower than those with COVID-19 caused by earlier virus strains." (PMID 37333991, 2023).
COVID-19 (continued). "Characteristic changes in hypercoagulation in severe COVID-19 patients include increased fibrinogen and thrombin levels, Factor VIII activity, and circulating vWF as well as exhausted fibrinolysis." (PMID 38143504, 2023). "ADAMTS13 and VWF are inappropriately regulated in SCD, similar to what is seen in COVID-19 patients." (PMID 37159776, 2023). "Indeed, coagulation abnormalities, including elevated levels of circulating fibrin degradation products and von Willebrand factor, the prolongation of prothrombin time, and thrombocytopenia, are detected in hospitalized and severely ill patients with COVID-19 and may have prognostic value." (PMID 35323682, 2022). "Genes whose expressions were altered in endothelial cells under the influence of COVID-19 included TIMP1, MMP2, MMP11, VWF, ICAM1, and ICAM2, which affect coagulation and the development of inflammation." (PMID 36551272, 2022). "The vWF:RCo/ADAMTS-13:activity (point 1), vWF/ADAMTS-13 (point 2) and vWF:RCo/ADAMTS-13:activity (point 2) ratios were significantly higher in patients with moderate and severe COVID-19." (PMID 35887770, 2022). "VWF also plays a role in secondary hemostasis, i.e., it protects coagulation factor VIII against proteolysis via active protein C. In the course of COVID-19, factor VIII activity also intensifies, becoming another component of the hypercoagulable state." (PMID 36551272, 2022). "Elevated levels of Von Willebrand factor (VWF), fibrinogen, and the fibrin degradation product D-dimer, along with a mildly prolonged prothrombin time (PT) and thromboelastographic data that indicates clot stability, all support a COVID-19 specific coagulopathy hypothesis." (PMID 36564503, 2022). "Sequential measurement of platelet indices, TAT, PAP, protein C, protein S, vWF, D-dimer, and PAI-1 following COVID-19 vaccination was informative." (PMID 35999558, 2022). "The increased levels of von Willebrand factor (VWF) antigen, D-dimers, and tissue plasminogen activator are reported in the COVID-19 group, substantiating endothelial damage and pro coagulation in COVID-19 infection." (PMID 35600485, 2022). "In the light of the presented data, it seems promising to further study the role of vWF and ADAMTS-13 in the development of complications of COVID-19 as well as to study their relationship with the long-term outcomes of this disease." (PMID 35887770, 2022). "In a meta-analysis that included 1187 patients from 17 studies, VWF antigen, PAI-1, t-PA, sTM were predictors of worse outcome in COVID-19 patients." (PMID 35524223, 2022). "EC biomarkers including vWF: Ag, vWF propeptide (vWFpp) and Factor VIII (FVIII: C) are significantly elevated in convalescent COVID-19 patients." (PMID 35449732, 2022). "Other factors such as von Willebrand Factor (vWF) and Factor VIII (FVIII), were elevated in COVID-19 in a French study." (PMID 35111367, 2022). "Part of the increased level of EVs, which is characteristic of severe COVID-19 and associated ARDS, is due to endothelial injury, whether released from the pulmonary capillary vasculature (angiotensin-converting enzyme+ [ACE+]; von Willebrand Factor− [vWF−]) or systemic vasculature (ACE−; vWF+)." (PMID 36268783, 2022). "In the present cohort of COVID-19 patients, thrombomodulin, IL-6, FVIII, VWF:Ag, sEPCR, sC5b9, tPA, PAI-1 activity, C4, ICAM-1 and VCAM-1 plasma levels were higher than normal ranges, in line with previous studies that included patients with a severe disease." (PMID 36143072, 2022). "The activity and antigen of Von Willebrand factor (vWF) and factor VIII were considerably elevated in patients with COVID-19, indicating an inflammation-mediated endothelial activation procoagulant state." (PMID 35557984, 2022). "This contrasts with a recent study reporting a correlation between VWF and mortality in ICU COVID-19 patients." (PMID 35740360, 2022).
COVID-19 (continued). "A high incidence of thrombosis, shown by increased immunostaining intensity for VWF in pulmonary vascular endothelium of patients with a disease duration of more than 10 days, confirmed the hypothesis of circulatory disorder progression during the entire period of COVID-19." (PMID 35215805, 2022). "The elevated vWF and decreased ADAMTS13 levels are the potent predictors of adverse outcomes in severe COVID-19 patients." (PMID 36466841, 2022). "The plasma levels of vWF, angiopoietin-2, Fms-related tyrosine kinase 3 ligand (FLT-3L), and PAI-1 are significantly elevated in patients with COVID-19 (Liu and Zhang, 2021)." (PMID 36519165, 2022). "vWF, an adhesive glycoprotein synthesized by endothelial cells and megakaryocytes, and coagulation factor VIII seems to be the main players in AIS COVID-19 clot formation in our study." (PMID 36704480, 2022). "Lastly, a distinctive feature of COVID-19 lies in the coagulation/fibrinolytic abnormalities defined as elevated plasma levels of D-dimer, factor VIII, and von Willebrand factor." (PMID 34572407, 2021). "We detected increased expression of vWF and FVIII in LSECs from liver samples from patients with COVID-19." (PMID 34291736, 2021). "Especially for blood coagulation, a recent study revealed that plasma von Willebrand factor antigen (VWF:Ag) and pro-coagulant factor VIII (FVIII) levels, as well as plasma VWF propeptide (VWFpp), markedly increased in COVID-19 patients." (PMID 33801921, 2021). "Subsequently, the VWF:AG/ADAMTS13 activity ratios in COVID-19 (+) patients (Median:6.051 and IQR:3.824–10.17) were significantly higher (p < 0.0001) than COVID-19 (−) patients (Median:5.567 and IQR:3.352–8.245)." (PMID 35087853, 2021). "The data suggests that increased VWF:AG levels and VWF:CBA in plasmas of COVID-19 (+) patients occurred despite normal ADAMTS13 function." (PMID 35087853, 2021). "A comparison between healthy plasma and acute COVID-19 solubilized clots also showed a significant increase in coagulation factor XIII A chain, VWF Complement component C7 and CRP." (PMID 34328172, 2021). "In response to the first published GWAS of COVID-19, we reported findings that link the ABO signal with a number of clinically actionable targets including coagulation factors (von Willebrand factor [vWF], and Factor VIII [F8]), IL-6, and CD209/DC-SIGN." (PMID 34402426, 2021). "High levels of von Willebrand Factor antigen and its activity, and factor VIII (FVIII) activity in ICU-admitted COVID-19 patients indicate endothelial activation." (PMID 34177896, 2021). "Markers of endothelial cell activation, such as increased circulating vWF and FVIII, have been observed in patients with severe COVID-19 in hospital intensive care units; these markers are correlated with mortality." (PMID 34291736, 2021). "A recent study demonstrate that coagulation biomarkers are independent predictors of increased oxygen requirement in COVID-19 patients, among them increased fibrinogen and decreased FVIII/VWF:Ag ratio." (PMID 34150806, 2021). "A close relationship with the VWF/ADAMTS13 axis and hospitalized COVID-19 (+) patients disease severity (low, intermediate, and high) is identified." (PMID 35087853, 2021). "At present, several studies have reported that plasma VWF levels, together with FVIII, were higher in COVID-19 subjects." (PMID 33664450, 2021). "The differences in VWF, ADAMTS13, thrombin generation, and plasmin generation parameters were evaluated in plasmas from COVID-19 (+) and COVID-19 (−) patients that were <65 and ≥65 years of age." (PMID 35087853, 2021). "COVID-19 patients have significantly elevated vWF, which can spontaneously bind platelets and lead to microthrombosis, and may mechanistically link the overrepresentation of blood group A individuals among severe COVID-19, as vWF levels are known to be higher in such individuals." (PMID 33604758, 2021).